FBXW7 (F-box and WD repeat domain containing 7)
Diseases named in the same sentence as FBXW7 in open-access papers (continued):
Sharing a sentence is not in itself a finding about the gene and the disease.
tumor (continued). "FBXW7 plays a crucial role as a tumor suppressor and is among the most frequently observed ubiquitin–proteasome system proteins in human cancer." (PMID 38349431, 2024). "Then, we enriched CSCs by inducing tumor sphere formation in the TNBC cell lines HCC1937 and MDA-MB-231, measured the mRNA and protein levels of FBXW7, and found that FBXW7 was downregulated in tumor spheres compared to the corresponding adherent cells." (PMID 38268032, 2024). "For instance, MiR-27a-3p and MiR-92a-3p downregulate FBXW7 mRNA expression, promoting tumor cell proliferation and invasion." (PMID 39749199, 2024). "FBXW7 functions as a tumor suppressor gene by regulating the degradation of oncoproteins, such as c-MYC, suggesting a tumor-suppressive role of m6A specifically in this cellular context." (PMID 38444581, 2024). "Previous investigations have revealed that the ubiquitin ligase FBXW7 modulates epithelial-mesenchymal transition and tumour metastasis." (PMID 38494478, 2024). "Research has demonstrated that deletion of FBXW7 in tumour cells leads to mitotic defects and chromosomal instability, promoting tumorigenesis." (PMID 39031722, 2024). "FBXW7 (F-box and WD repeat domain-containing 7), a critical member of the F-box protein family, functions as a vital tumor suppressor but is inactivated in HCC." (PMID 38927059, 2024). "Despite some understanding of how FBXW7 defects cause aberrant SCF complex function, only a few studies have identified targets that selectively target FBXW7‐defective tumour cells." (PMID 37866880, 2024). "In part at least, the tumour suppressive role of FBXW7 has been ascribed to its ability to drive the ubiquitination and degradation of oncoproteins including c‐MYC, NOTCH, c‐JUN, Cyclin E and MCL1, as well as pro‐aneuploidy factors such as Aurora A." (PMID 37866880, 2024). "FBXW7 is a crucial tumor suppressor and one of the most deregulated ubiquitin-proteasome system proteins in human cancer and is regulated by miRNA-223." (PMID 39200178, 2024). "It is widely known that FBXW7 is a critical tumor suppressor which is commonly inactivated in human lung, gastric, breast and several other cancers through genetic and epigenetic mechanisms, along with post transcriptional modifications." (PMID 38454442, 2024). "FBXW7 deficiency in ESCC can overactivate the ANXA2-ERK pathway, worsening the tumor’s biological behavior." (PMID 39749199, 2024). "Understanding the functional regulatory network of FBXW7 in greater depth is essential to elucidate its tumor-suppressive effects and to identify potential avenues for developing new cancer treatment strategies." (PMID 39749199, 2024). "Overexpression of FBXW7 directly ubiquitinates and degrades β-catenin, thereby preventing pathway overactivation and inhibiting tumor growth and invasion." (PMID 39749199, 2024). "The results suggested that FBXW7 overexpression significantly inhibited tumor growth and decreased tumor size and tumor weight compared with that in the vector control group, while the opposite trends were observed following FBXW7 knockdown." (PMID 38268032, 2024). "Upregulation of MiR-27a-3p in ESCC has been shown to reduce FBXW7 expression, leading to accelerated tumor proliferation and disease progression." (PMID 39749199, 2024). "Low expression of Fbxw7 was found in both HCC and ICC, and was associated with poor prognosis, advanced tumor stages, and metastasis." (PMID 38212325, 2024).
tumor (continued). "Fbxw7 is also a critical tumor suppressor in many cancers and functions as a substrate recognition component of the SCF E3 ubiquitin-protein ligase complex." (PMID 38212325, 2024). "In cancer, miRNAs can suppress FBXW7 expression, thereby disrupting its tumor-suppressive functions." (PMID 39749199, 2024). "FBXW7 plays a pivotal role as a tumor suppressor by orchestrating the proteasome-driven degradation of oncoproteins, including but not limited to c-MYC, MCL1, Notch1/4, cyclin E and mTOR." (PMID 38444581, 2024). "MT1JP adsorbs miR-92a-3p to target and regulate the expression of FBXW7, which is a tumor suppressor molecule that plays an important role in tumor apoptosis, epithelial cell differentiation, and drug resistance in GC." (PMID 39210921, 2024). "For Chinese patients, the results also suggest that GC patients with low expression of FBXW7 have poor tumor differentiation and worse prognosis (Li MR." (PMID 39749199, 2024). "We found that forced expression of FBXW7 induced cell apoptosis and cell cycle arrest at the G1 phase in HCC1937 cells, but FBXW7 knockdown reversed the tumor-inhibiting effect of FBXW7 overexpression on the cell cycle and apoptosis in MDA-MB-231 cells." (PMID 38268032, 2024). "The tumour‐suppressive role of FBXW7 is ascribed to its ability to drive ubiquitination and degradation of oncoproteins." (PMID 37866880, 2024). "USP9X inhibits FBXW7 autoubiquitination, thereby reducing the activity of its downstream substrate c-Myc and suppressing tumor formation in mice." (PMID 39749199, 2024). "FBXW7 primarily targets oncoproteins for degradation and is thus widely recognized as a classic tumor suppressor gene." (PMID 38268032, 2024). "Extensive research has demonstrated that abnormal FBXW7 expression contributes to tumor initiation, progression, treatment resistance, and poor prognosis in cancer patients." (PMID 39749199, 2024). "FBXW7, a tumour suppressor, can recognize the substrates, namely, Cyclin E, c-Myc, Mcl, mTOR, Jun, and NOTCH, for the component of the SCF E3 ubiquitin ligase." (PMID 36936374, 2023). "FBXW7 is critical tumor suppressor that is widely involved in various physiological processes including cell proliferation, differentiation, and apoptosis." (PMID 37249289, 2023). "At 4 weeks after injection, CAL27 cells with FBXW7 overexpression had significantly lower tumor weight in nude mice." (PMID 37249289, 2023). "FBXW7 is involved in immune evasion that occurs in anti-tumor immune responses, as well as in the regulation of the immune microenvironment, and its mutation or downregulation is more likely to lead to immunotherapy resistance." (PMID 38027013, 2023). "Initially, FBXW7 has been considered as a tumor suppressor, and there is growing evidence showing that FBXW7-mediated ubiquitination is able to exert regulatory effects on cell cycle, proliferation, differentiation, and apoptosis." (PMID 37082613, 2023). "A four-gene panel consisting of ARID1A, CTNNB1, FBXW7 and PPP2R1A was used to investigate mutations in gynaecologic tumour tissue." (PMID 36982928, 2023). "In vivo experiments have also demonstrated that overexpression of FBXW7 can rescue the anti-tumor effects attenuated by METTL3 knockdown." (PMID 36998461, 2023). "Recently, several studies have confirmed the important role of F-box and WD Repeat Domain-containing-7 (FBXW7) in the development of tumor resistance." (PMID 38027013, 2023). "Another interesting target of FBXO45, FBXW7, is a tumour suppressor that targets specific substrates for ubiquitination and degradation, including the known driver oncogenes of aggressive PCA MYC and Mcl-1." (PMID 36980776, 2023). "We have proved that FBXW7 regulate tumor cell autophagy through the regulation of the protein levels of BECN1, Atg7, and LC3." (PMID 37249289, 2023). "One potential method to restore FBXW7 expression in tumor cells with wild-type FBXW7 mRNA is to target FBXW7-miRNAs." (PMID 37408248, 2023).
tumor (continued). "FBXW7 is a main tumor suppressor due to its ability to control proteasome-mediated degradation of several oncoproteins such as c-Jun, c-Myc, Cyclin E1, mTOR, and Notch1-IC." (PMID 36934104, 2023). "FBXW7 is a central tumor suppressor governing cell cycle progression, cell growth, and tumor development by targeting several oncoproteins for ubiquitin-mediated proteolysis." (PMID 36934104, 2023). "The manipulation of these kinases is considered a useful strategy to modulate FBXW7-dependent cell signaling pathways and tumor suppressor functions." (PMID 36934104, 2023). "It has been shown that overexpression of miR-182 by interacting with 3’UTR of FBXW7, a gene involved in the ubiquitination of oncoproteins, suppressed the translation of this anti-tumor gene and reduced its expression." (PMID 37438760, 2023). "Another study reports an association between HSF1 and F-box and WD repeat domain-containing protein 7 (FBXW7), an important tumor suppressor for human cancer." (PMID 37958341, 2023). "The FBXW7 gene has been identified as a tumor suppressor in ovarian cancer (OC), as reported in studies." (PMID 37408248, 2023). "Concomitant with its tumour‐suppressive role, FBXW7 is frequently underexpressed or inactivated in most human cancers." (PMID 36881608, 2023). "Our pilot study investigated mRNA expression of the SWI/SNF chromatin-remodelling complex gene ARID1A, NOTCH receptors, WNT pathway genes CTNNB1 and FBXW7 mRNA expression in two OC cell cultures as well as 51 gynaecologic tumour tissues." (PMID 36982928, 2023). "FBXW7 was recognized as a critical tumor suppressor gene and a part of the SCF (SKP1-CUL1-F-box protein) complex, an E3 ubiquitin ligase that conducts protein ubiquitylation and stimulates subsequential proteosome-mediated degradation." (PMID 37064111, 2023). "In CC, miR-92a is significantly upregulated and binds to the 3′UTR of FBXW7, inhibiting its expression and promoting tumor progression and invasion." (PMID 37408248, 2023). "Here, we performed in vitro assays, in silico studies, western blots and luciferase reporter assays and found that miR-92b regulates the expression of FBXW7, a recognized tumor suppressor gene." (PMID 37752997, 2023). "FBXW7, on the other hand, is an established tumour suppressor that functions as SCF substrate recognition protein targeting several oncogenic proteins including cyclin E and c‐MYC for proteasome degradation." (PMID 36881608, 2023). "FBXW7 protein expression has been inversely correlated with poor prognosis and resistance to chemotherapy in a variety of tumor types." (PMID 36934104, 2023). "Altogether, this work reveals a new regulatory axis, DYRK2/FBXW7, which provides an understanding of the role of these two proteins in tumor progression and DNA damage responses." (PMID 36934104, 2023). "Recent studies suggested that FBXW7 contributes to tumor metastasis, because increasing FBXW7 reduces cancer metastasis and EMT." (PMID 37635248, 2023). "Mutation or loss of function of FBXW7 significantly reduces the infiltration of dendritic cells and immune cells, such as macrophages and CD8 T cells, in the tumor microenvironment, thereby promoting resistance to anti-PD-1 therapy." (PMID 38027013, 2023). "Although the mechanisms by which autophagy promotes tumor drug resistance are not fully understood, the roles of FBXW7 in regulating autophagy to influence drug resistance are emerging." (PMID 38027013, 2023). "FBXW11 and FBXW7 are two important F-box proteins of the ubiquitin-proteasome system (UPS) that have been recognized as tumor suppressors, by targeting oncogenic proteins, in a different variety of human cancers." (PMID 37438760, 2023).
tumor (continued). "Among approximately 70 F-box proteins that have been identified in humans, FBXW7 (also known as FBW7, hCDC4, hAGO, or Sel10) has the highest frequency of mutations in cancer, indicating its crucial role as a tumor suppressor in oncopathogenesis." (PMID 37408248, 2023). "Taken together, our findings suggest that the dysregulated expression of miR-92b in GBM contributes to tumor progression by targeting FBXW7." (PMID 37752997, 2023). "Previous studies of FBXW7 focused on its functions in tumor cells, and little is known about the role of this protein in stromal cells in the host microenvironment." (PMID 37208442, 2023). "Alterations of NF2 (40%) and FBXW7 (30%) were also identified in tumors only, indicating a heterogeneity of tumor cells and clonal selection process in some patient-derived cell lines during the expansion process in vitro." (PMID 37345150, 2023). "Aberrant FBXW7 is involved in the development of cancer drug resistance (apoptosis resistance, EMT, stem cell characterization, shaping of the tumor microenvironment, autophagy and immune evasion) by causing an imbalance in oncoproteins." (PMID 38027013, 2023). "Apart from FBXW7, other F-box proteins also impact tumor drug resistance by regulating the corresponding substrate proteins." (PMID 36998461, 2023). "We summarize the general mechanism by which FBXW7 is involved in tumor resistance through the available literature and describe the development of FBXW7 resistance in a variety of human tumors." (PMID 38027013, 2023). "In the subsequent sections, we will describe the mechanism of FBXW7 involvement in tumor drug resistance, its application in specific solid tumors, and therapeutic strategies targeting FBXW7." (PMID 38027013, 2023). "This inhibition of miRNAs results in an increase in FBXW7 expression, which leads to the degradation of the corresponding substrate and an increase in tumor sensitivity to drugs." (PMID 36998461, 2023). "Mutations of ARID2, CUL3, TET1, FBXW7, EZR and GPHN were frequently accompanied by copy number loss consistent with their predicted/documented tumour suppressor roles." (PMID 38106039, 2023). "TTN-AS1 regulates FBXW7 expression by modulating miR-15b-5p, exerting a tumor-suppressive role in the development of OC." (PMID 37408248, 2023). "For example, alterations in the oncogenic driver genes FBXW7 (a negative regulator of cyclin E, encoded by CCNE1) and CCNE1 were observed in 6 patients across multiple tumour types (CRC, HGSOC, NSCLC)." (PMID 37120671, 2023). "Through degradation of its substrates, FBXW7 plays a pivotal role in drug resistance in tumor cells and shows the potential to rescue the sensitivity of cancer cells to drug treatment." (PMID 36998461, 2023). "Additionally, PI3K, AKT, and mammalian target of rapamycin (mTOR) inhibitors may serve as potential therapeutic options for patients with PIK3CA and PTEN mutations, whereas an mTOR inhibitor can be used as a therapeutic approach for targeting STK11- and FBXW7-deficient tumours." (PMID 38024139, 2023). "FBXW7 (also known as CDC4) is a component of the S-phase kinase-associated protein 1 (SKP1)/CUL1/F-box (SCF) E3 ubiquitin ligase complex, which functions as a tumor suppressor which is frequently altered in cancer." (PMID 36694209, 2023). "Most of these substrates are well-known oncogenic proteins frequently overexpressed in various human cancers, leading to FBXW7 being considered a tumor suppressor that negatively regulates these proteins." (PMID 36998461, 2023).
tumor (continued). "It is possible that the role of FBXW7 is context-dependent and that its mediation of signaling cascade control extends beyond the reduction of tumor resistance." (PMID 37658431, 2023). "What’s more, some experiments using FBXW7 knockout mouse models constructed by knocking out the gene in embryonic stem cells have also demonstrated that abnormal expression of FBXW7 leads to tumor formation." (PMID 36998461, 2023). "The FBXW7 proteins in the F‐box protein family were found to play a role in tumor protein phosphorylation‐dependent ubiquitination and proteasomal degradation." (PMID 36860568, 2023). "TRP120 ligase maintains the stability of Notch and other tumor proteins involved in cell survival and apoptosis by degrading FBXW7, thereby downregulating the innate immune host defense system and promoting ehrlichiosis." (PMID 36998461, 2023). "Inhibition of FBXW7 by miRNA weakens its regulatory effect on downstream substances, affecting the sensitivity of each tumor to drugs." (PMID 36998461, 2023). "Our pilot study investigated the expression of ARID1A and the NOTCH receptors and WNT components CTNNB1 and FBXW7 in two OC cell cultures, then validated the results in gynaecologic tumour tissues." (PMID 36982928, 2023). "Enforced circ-FBXW7 stimulated symmetric differentiation dividing, which consequently resulted in spheres forming inhibition, and affected the tumor formation." (PMID 37393311, 2023). "FBXW7 is a critical tumour suppressor and is able to control proteasome-mediated degradation of oncoproteins." (PMID 37046316, 2023). "Here, we review the mechanisms of the regulation on FBXW7 and its tumor suppression role in immune filed among various diseases (mostly cancers) to explore novel immune targets and treatments." (PMID 35814468, 2022). "As detailed above, activation of specific signaling pathways that promote tumor cell proliferation, cell cycle progression, or oncogenesis, such as Erk1/2, Pin1 and PLK1, have been associated with FBXW7 auto-ubiquitination and degradation." (PMID 35346215, 2022). "And F-box and WD repeat-domain containing protein 7 (FBXW7), a well-known tumor suppressor in many cancer types, was identified as a direct target of miR-103a-3p." (PMID 35094292, 2022). "FBXW7 reshapes the proliferative niches of tumor cells through ubiquitinating and degrading several crucial signal molecules, such as c-MYC, c-Jun, phosphatidylinositol 3-kinase (PI3K)/AKT, mTOR, Notch, as well as JAK/STAT signaling pathway." (PMID 35515121, 2022). "FBXW7, a well-known tumor suppressor, has been demonstrated to control the degradation of some oncoproteins such as cyclin E, c-Myc, Yap and Notch2." (PMID 35094292, 2022). "The sphere formation assay also showed that the downregulation of FBXW7 promoted the size and generation of tumor spheres." (PMID 36159747, 2022). "Myeloid cell-specific ablation of FBXW7 enhances tumor proliferation by decreasing its ubiquitination on c-MYC, which promotes TAM polarization." (PMID 35515121, 2022). "Protein levels of FBXW7 have also frequently been found to be lower in CRC tumor tissue in comparison to normal tissue." (PMID 35715570, 2022). "F-box and WD repeat domain containing 7(FBXW7), one of the ubiquitin-proteasome system proteins, is an essential tumor suppressor and is frequently deregulated in human cancer cells." (PMID 35165511, 2022). "F-box and WD repeat domain containing seven (FBXW7), a known E3 ubiquitin ligase involved in ubiquitylation and proteasomal degradation of c-Myc, is an important tumor suppressor and is commonly dysregulated in human cancers." (PMID 35064102, 2022). "Given that FBXW7 is a well-established tumor suppressor, FBXW7 inactivation should theoretically promote cancer cell growth." (PMID 36104351, 2022).